CTNNBL1 (catenin beta like 1)
Description:
Component of the PRP19-CDC5L complex that forms an integral part of the spliceosome and is required for activating pre-mRNA splicing. Participates in AID/AICDA-mediated somatic hypermutation (SHM) and class-switch recombination (CSR), 2 processes resulting in the production of high-affinity, mutated isotype-switched antibodies.
Synonyms: NAP; C20orf33; PP8304; FLJ21108; P14L; P14; NYD-SP19; IMD99; dJ633O20.1
Tractability: Small molecule: a structure with a bound ligand is known. PROTAC: ubiquitination databases record sites on it; its protein half-life has been measured.
Gene: Protein-coding gene on chromosome 20 (37,694,030 to 37,872,129, forward strand). Ensembl gene ENSG00000132792.
Subcellular location: Nucleus (Isoform 1); Cytoplasm (Isoform 2)
Subcellular location (Human Protein Atlas): Nucleoplasm; Centrosome; Cytosol
Pathways (Reactome):
Disease: Dengue Virus-Host Interactions
Metabolism of RNA: mRNA Splicing - Major Pathway
Gene Ontology:
Molecular function: enzyme binding; protein binding
Biological process: positive regulation of apoptotic process; somatic diversification of immunoglobulins; mRNA splicing, via spliceosome; gene expression
Cellular component: membrane; nucleoplasm; nucleus; Prp19 complex; spliceosomal complex; cytoplasm
Genetic constraint (gnomAD): Loss-of-function variants: 26 observed, 55.72 expected, observed/expected ratio (o/e) 0.47, 90% interval 0.34 to 0.65. The upper end of that interval is the gene's LOEUF score, 0.65, which puts it in group 2 of 6, group 1 being the genes least tolerant of losing a copy. Missense variants: 446 observed, 621 expected, observed/expected ratio (o/e) 0.72, 90% interval 0.66 to 0.78. Synonymous variants: 199 observed, 234.85 expected, observed/expected ratio (o/e) 0.85, 90% interval 0.75 to 0.95.
Gene-disease validity (ClinGen):
ClinGen rates the evidence that CTNNBL1 causes each of these diseases.
common variable immunodeficiency (autosomal recessive): Limited.
Homologues: Orthologues: chimpanzee CTNNBL1 (99% identical), guinea pig CTNNBL1 (97% identical), pig CTNNBL1 (97% identical), mouse Ctnnbl1 (96% identical), macaque CTNNBL1 (95% identical), dog CTNNBL1 (94% identical), rat Ctnnbl1 (91% identical), rabbit CTNNBL1 (91% identical), tropical clawed frog ctnnbl1 (79% identical), zebrafish ctnnbl1 (79% identical), Drosophila melanogaster CG11964 (56% identical), Caenorhabditis elegans ctnb-1 (44% identical).
Diseases named in the same sentence as CTNNBL1 in open-access papers:
CTNNBL1 is named in the same sentence as 23 diseases in open-access papers, as found by Europe PMC text mining. Sharing a sentence is not in itself a finding about the gene and the disease. The quoted sentences say what the papers report.
Obesity (12 papers, 2009 to 2020). Accumulation of substantial excess body fat. "The Chromosome 2 locus contains Ctnnbl1, a gene implicated in obesity and two interesting candidates, bactericidal/permeability-increasing protein (Bpi) and lipopolysaccharide binding protein (Lpb)." (PMID 26260972, 2015). "For example, the CTNNBL1 gene was recently implicated in the development of obesity in a genome-wide association study using both BMI (most significant SNP: P = 2.69×10-7) and body fat mass (P = 4.99×10-8) as obesity phenotypes." (PMID 21747914, 2011). "A recent genome-wide association (GWA) study of U.S. Caucasians suggested that eight single nucleotide polymorphisms (SNPs) in CTNNBL1 are associated with obesity and increased fat mass." (PMID 19228371, 2009). "Both CTNNBL1 variants associated with body weight and height, whereas BMI and waist circumference was insignificantly elevated with increasing number of obesity risk alleles." (PMID 19245693, 2009). "This is consistent with the results from Liu and co-workers, who in a GWA scan identified five SNPs in CTNNBL1 as novel obesity variants, associating with both BMI and fat mass as quantitative measures." (PMID 19245693, 2009). "CTNNBL1 variants associated with body weight and height, and confer the risk of developing obesity in meta-analyses combining the present and a previous study." (PMID 19245693, 2009). "The CTNNBL1 gene is associated with obesity, a known risk factor for the development of CRC." (PMID 26101583, 2015). "That variants in CTNNBL1 could confer risk to the development of morbid obesity is supported by the meta-analyses performed including the present study and the French Caucasian obesity case-control sample used for replication in the initial study." (PMID 19245693, 2009). "First, we aimed to replicate the association of the obesity risk alleles (rs6013029 T-allele, rs16986921 T-allele, rs6020712 A-allele, rs6020846 G-allele, rs6020395 C-allele, rs16986890 G-allele, rs6096781 C-allele, and rs6020339 C-allele) of CTNNBL1 in two GWA data sets." (PMID 19228371, 2009). "The top predictors, rs10521308 (FTO), rs2206135 (CTNNBL1), cg13438334 (DGAT1), and cg22390041 (ALDH4A1) are located in genes known to be associated with obesity risk." (PMID 30255820, 2018). "A recent GWA scan in 1,000 US Caucasians with measures available on BMI and fat mass, identified two novel obesity gene loci in the proximity of FDFT1 (farnesyl-diphosphate farnesyltransferase 1) and CTNNBL1 (catenin (cadherin-associated protein), β-like 1)." (PMID 19245693, 2009). "We aimed at replicating the observed association between the CTNNBL1 rs6013029 T-allele, CTNNBL1 rs6020846 G-allele, and FDFT1 rs7001819 C-allele and measures of obesity." (PMID 19245693, 2009). "Linkage scans of obesity have previously highlighted the chromosome 20q11 region, which encompasses CTNNBL1, as a candidate region, thus, further establishing the candidature of this gene in the pathogenesis of obesity." (PMID 19245693, 2009). "Our data confirmed the role of FTO, CTNNBL1, LEPR and PPARG in obesity predisposition." (PMID 24879436, 2014). "Further studies have to be performed to validate or not the initial findings about the association of CTNNBL1 variants and obesity." (PMID 19228371, 2009). "We did not detect confirmation of association of variants in CTNNBL1 with obesity in a population of Central European ancestry." (PMID 19228371, 2009). "We detected no confirmation of the recent association of variants in CTNNBL1 with obesity in a population of Central European ancestry." (PMID 19228371, 2009). "We investigated whether variants in CTNNBL1 (including rs6013029) and in three other genes (SH3PXD2B, SLIT3 and FLJ42133,) were associated with obesity." (PMID 19228371, 2009). "The link between FDFT1, CTNNBL1 and obesity is fairly unknown." (PMID 19245693, 2009).
ovarian carcinoma (4 papers, 2015 to 2023). A malignant neoplasm originating from the surface ovarian epithelium. "With regard to CTNNBL1, UQCC1 and CKB, all of them have been previously associated to ovarian cancer." (PMID 35120576, 2022). "CTNNBL1 is overexpressed in ovarian cancer cell lines and related to poor prognosis." (PMID 37077419, 2023).
breast carcinoma (2 papers, 2017 to 2025). "The 3′ member of the KRI1-ATRX fusion (ATRX) has been previously associated with childhood neuroblastoma and the 3′ member of the CACNA1D-CTNNBL1 fusion (CTNNBL1), is associated with an anti-apoptotic, tumor suppressive function consistent with its reduced expression in our breast cancer samples." (PMID 28851357, 2017).
morbid obesity (2 papers, 2009 to 2014). An excess of body weight, normally defined as an individual with a body mass index greater than 35 or a body weight greater than one hundred percent of ideal body weight. "The most significantly associating variants within CTNNBL1 including rs6013029 and rs6020846 were additionally confirmed to associate with morbid obesity in a French Caucasian case-control sample." (PMID 19245693, 2009). "Contrary, meta-analyses indicates that both the CTNNBL1 rs6013029 T-allele and the rs6020846 G-allele confer the risk of being obese and especially morbidly obese, however, large well-powered studies designed to analyse especially morbid obesity are needed to validate this observation." (PMID 19245693, 2009).
serous ovarian carcinoma (2 papers, 2021 to 2022). "Specifically, the spliceosome-associated factor CTNNBL1, has been related to proliferation and invasion in HGSOC, at least partially through regulation of FOXM1 splicing, Notably, the FOXM1 signaling pathway is activated in 84% high-grade serous ovarian cancer and linked to platinum resistance." (PMID 35120576, 2022).
cognitive decline (1 paper, 2025). "Higher levels of NNT, MYO15A, and GCA were protective in females; greater expression of PEPD, CTNNBL1, MVB12A, XKR8, WBP1L, and GALNT7-DT were associated with faster cognitive decline in females." (PMID 40166028, 2025).
colon cancer (1 paper, 2015). "Further experiments are necessary to investigate the epigenetic regulation of CTNNBL1 in colon cancer cells and patient specimens." (PMID 26101583, 2015). "However, the potential epigenetic regulation of CTNNBL1 in colon cancer remains to be elucidated." (PMID 26101583, 2015).
COVID-19 (1 paper, 2024). A disease caused by infection with severe acute respiratory syndrome coronavirus 2. "Catenin Beta Like 1 (CTNNBL1) exhibited specific upregulation in the COVID-19 comparison group (log2FC=1.41, Q value=0.03)." (PMID 39301288, 2024).
microcephaly (1 paper, 2022). A congenital or acquired developmental disorder in which the circumference of the head is smaller than normal for the person's age and sex. "Five direct known interactions were found between HLHS candidates and microcephaly-associated genes (HLHS candidates are shown in bold): TSC1-POGZ, TSC1-CDK6, CTNNBL1-STAMBP, TRAPPC2L-TRAPPC6B and TSC22D1-QARS1." (PMID 35456433, 2022).
schizophrenia (1 paper, 2025). A major psychotic disorder characterized by abnormalities in the perception or expression of reality. "XKR823, 24 and WBP1L25 are related to other disorders, such as schizophrenia, and CTNNBL1 has previously been associated with memory in a young, cognitively healthy cohort." (PMID 40166028, 2025).
tumor (4 papers, 2017 to 2025). "Interestingly, as depicted in the Polar chart, when considering the specific gene deregulation associated to drug sensitivity, CTNNBL1, RNF24 and TTI1 showed in primary HGSOC cell lines the same trend observed in tumor tissue from HGSOC patients." (PMID 35120576, 2022). "Interestingly, we showed that CTNNBL1, RNF24 and TTI1 are associated to resistance to therapy in both primary HGSOC cell lines and patients’ samples, in line with available literature data on the role of these proteins as tumor cell-derived resistance factors." (PMID 35120576, 2022). "Cytotoxicity assays, combined with gene-expression analysis in primary HGSOC cell lines, allowed to define CTNNBL1, RNF24, and TTI1 as cell-autonomous contributors to tumor resistance." (PMID 35120576, 2022).
CTNNBL1 also shares sentences with these, for which no sentence is quoted: cancer (4 papers); neuroblastoma (2); brain malformations (1); cognitive disorder (1); colorectal cancer (1); diabetes (1); hypertriglyceridemia (1); infection (1); liver cancer (1); lymphoma (1); skin infection (1); type 2 diabetic (1).